TNF (tumor necrosis factor)
Diseases named in the same sentence as TNF in open-access papers (continued):
Sharing a sentence is not in itself a finding about the gene and the disease.
psoriasis (continued). "Moreover, cases of patients with psoriasis or other chronic inflammatory systemic diseases treated with IL-17A inhibitors, IL-12/23 inhibitors, IL-23 inhibitors or TNF-α inhibitors developing eczematous paradoxical reactions, as well as paradoxical psoriasis, have been reported." (PMID 39161766, 2024). "Additionally, anti-tumor necrosis factor (anti-TNF) agents and other immunosuppressive medications, like methotrexate and cyclosporine, occasionally employed in psoriasis management, may also heighten the risk of pulmonary infections, including SARS-CoV-2." (PMID 38400161, 2024). "Moreover, KYNU is upregulated by TNF-α and IL-17 synergistically in the psoriasis." (PMID 39045230, 2024). "Therefore, both T cells and DC are involved in the occurrence of PAEs: T cells play an important role in the pathogenesis of psoriasis by producing cytokines, for example, TNFα and IL-17, which sustain inflammatory mechanisms for psoriasis lesions, while dendritic cells are key producers of IFNα." (PMID 39000125, 2024). "In addition, T-cell-derived IFN-γ and TNF-α stimulate numerous inflammatory pathways in resident skin cells, with each cytokine influencing different responses and exhibiting a degree of synergism in modulating the gene expression in psoriasis lesions." (PMID 38929716, 2024). "Although TNF-α is a well-studied molecule with numerous proven cases of involvement in psoriasis, we consider our findings important as the constant high levels of TNF-α despite systemic treatment could be a straightforward explanation for the chronicity of psoriasis." (PMID 39044928, 2024). "Conversely, the immunological patterns typical of paradoxical psoriasis by anti-TNF-α and acute psoriasis, including overexpression of innate immunity molecules and dermal infiltration of BDCA+ pDC, CD15+ neutrophils, and c-kit/CD117+ mast cells could not be found." (PMID 38495872, 2024). "Wang Jiafeng suggested that 10 μg/mL curcumenol and other active components in Curcuma could inhibit the excessive secretion of four inflammatory cytokines (IL-1β, interleukin-6, interleukin-8, and interleukin 33) induced by TNF-α to different degrees in the treatment of psoriasis." (PMID 38338400, 2024). "Furthermore, the relevance of the feedback between TNF-α and S100-proteins has been confirmed for inflammatory processes like arthritis and psoriasis and IL-6 is the top cytokine induced by S100A8/S100A9 in myeloid cells as shown in a genome wide transcriptome analysis." (PMID 37056775, 2023). "The inflammatory cascade in psoriasis is driven by plasmacytoid dendritic cells (pDCs) and myeloid dendritic cells (mDCs), leading to the production of various inflammatory mediators, including tumour necrosis factor (TNF)-α, interleukins (IL)-12, IL-17, IL-22, IL-23, and interferon (IFN)-γ." (PMID 38258034, 2023). "In psoriasis, MIR31HG was found to be elevated in psoriasis lesions and the upregulation of MIR31HG required IL-17A, IL-22, TNF-α, and IL-1α stimulation, demonstrating that nuclear factor kappa B inhibitor (NF-κB) signalling could be crucial crosstalk in psoriasis." (PMID 37636269, 2023). "However, psoriasis that is intractable to treatment with these agents has also been reported, suggesting that an immune axis other than TNF-α, IL-17, and IL-23 may be involved in the pathogenesis of psoriasis." (PMID 37834081, 2023). "Urate crystals activate the NLR family pyrin domain-containing three inflammasomes in macrophages, resulting in the production of active IL-1β and IL-18, and promote the production of TNF-α in monocytes, indicating that UA might increase the levels of inflammatory cytokines promoting psoriasis." (PMID 36902720, 2023). "Interestingly, we found significant positive correlation between the dyslipidemia and the levels of inflammatory cytokine TNF and ROS; this may suggest that the dyslipidemia acts as initiating signal in chronic inflammatory process in psoriasis." (PMID 37531036, 2023).
psoriasis (continued). "Our findings indicate that suppressing SIRT3 exacerbated IMQ-induced psoriasis-like inflammation by upregulating the levels of acetylated XBP1s, which subsequently enhanced its total protein levels and transcriptional activity and increased the production of IL-23a, IL-6, and TNF-α cytokines." (PMID 37275851, 2023). "In a murine model of imiquimod-induced psoriasis, oral administration of Staphylococcus aureus and Streptococcus danieliae led to skin inflammation and increased expression of TNF, and IL-17, supporting the hypothesis that intestinal dysbiosis may lead to clinical worsening of the disease." (PMID 37156688, 2023). "However, other research did not detect a difference in infection risk among users of TNF-α, IL-17, or IL-12/23 inhibitors in psoriasis or PsA." (PMID 38029150, 2023). "Some polymorphisms identified in genes such as TNF, IL12RB2, and IL12B could be also involved in the production, differentiation, or activity of Tregs, pointing to a genetic background of Treg dysfunction in psoriasis." (PMID 37628670, 2023). "Given the role of inflammation and endothelial dysfunction in migraine pathogenicity, it has been postulated that inflammation-induced endothelial dysfunction in psoriatic patients (via TNF-α, IL-12, and IL-23 axis) may be a possible mechanism linking psoriasis with migraine." (PMID 36681575, 2023). "Moreover, as Tong and coworkers suggested, TNF-a, IL-17A, and IL-23 could potentially be used as biomarkers for the measurement and monitoring of depression and anxiety in individuals with psoriasis." (PMID 37240864, 2023). "Inhibiting the LPS-induced NF-κB pathway allows Kaempferia to prevent keratinocytes and macrophages from producing the pro-inflammatory factors TNF-α, IL-1, IL-6, IL-17, IL-22, and IL-23, indicating that this plant may be a promising candidate for the creation of anti-psoriasis medications." (PMID 37828492, 2023). "However, it remains unclear what role ADRA2A plays in the anti-TNF response in psoriasis or psoriasis pathogenesis." (PMID 37631238, 2023). "Consequently, anti-TNF-α agents are effective in treating psoriasis." (PMID 37554338, 2023). "However, overexpression of TNF-α can result in autoimmune diseases, such as RA and psoriasis." (PMID 38004064, 2023). "Although the chronic inflammatory state in psoriasis patients may induce carcinogenic effects, psoriasis treatments like systemic therapy, ultraviolet (UV) radiation, and tumor necrosis factor (TNF)-α therapy may also put psoriasis patients at greater risk for CM." (PMID 37503344, 2023). "Furthermore, IL-17 acts synergistically with TNF-α to stimulate keratinocytes to produce inflammatory cytokines and chemokines to recruit more inflammatory cells, thus amplifying the inflammatory cascade, leading to the development of psoriasis." (PMID 38008779, 2023). "Therefore, it has been suggested that treatment targeting TNF-α, IL-23, and IL-17, which play a major role in shaping psoriasis pathology, may also contribute to the reduction in atherosclerosis." (PMID 36769825, 2023). "Based on our findings, we hypothesize that during the progression of psoriasis, Th1 and Th17-derived cytokines (such as TNFα and IL17A) may induce PARP2 in keratinocytes, which may turn down aromatase activity and estrogen synthesis in keratinocytes that may trigger NF-κB activation." (PMID 37351597, 2023). "Another study with 47 psoriasis patients, serum levels of IL-6, TNF-α and proinflammatory adipocytokines (leptin, resistin and visfatin) were higher in psoriasis patients and serum adiponectin (an anti-inflammatory cytokine) was lower in psoriasis patients relative to healthy controls." (PMID 37681925, 2023). "After TNF-α treatment, cells organized tightly and proliferated greatly (P<0.01); HO-1 expression dropped obviously, along with the increased OS/inflammatory indicators and the decreased antioxidants (P<0.05); consequently, psoriasis-like cell models were well established." (PMID 36178125, 2022).
psoriasis (continued). "Interestingly, the 7KC-mediated promotion of TNF-α secretion from inflammatory cells in the skin may trigger an inflammatory loop between the liver and skin, contributing to the promotion of psoriasis-like dermatitis." (PMID 36555497, 2022). "Although the etiopathogenesis of psoriasis is multifactorial, its clinical manifestation mainly results from both uncontrolled keratinocyte proliferation and the overproduction of inflammatory mediators, such as tumor necrosis factor-α (TNF-α), interleukin (IL)-17, IL-12, and IL-23." (PMID 35329831, 2022). "Although specific anti-inflammatory signaling pathways of noscapine in psoriasis induction are undefined, based on the current study results, we proposed that noscapine's antiproliferative and anti-inflammatory effect operates through the suppression of TNF-α/IFNγ/IL-23." (PMID 35497929, 2022). "Therefore, even if R. mucosa is unlikely to specifically modulate each of the immunologic pathways that distinguish the AD and psoriasis, modulation of TNF signalling along with increased ceramide-family lipids would be expected to provide utility to any inflammatory skin disease." (PMID 36605199, 2022). "Treatment with RGRN-305 resulted in a marked inhibition of the IL-23, TNF-α, and IL-17A signaling pathways and the normalization of both histological changes and the gene expression profiles of psoriasis, further supporting that Hsp90 may serve as a novel target in the treatment of psoriasis." (PMID 36009046, 2022). "The first biological drugs used for the treatment of psoriasis, tumor necrosis factor alpha inhibitors, have long been used in combination with traditional topical and systemic therapies to induce a complete remission of the disease that could not be achieved with innovative drug alone." (PMID 35959523, 2022). "It seems that PAD-4 may be considered a psoriasis marker (with TNFα and IL-8)." (PMID 35163760, 2022). "Psoriasis onset is triggered when genetic and/or environmental factors activate plasmacytoid dendritic cells, resulting in the production of numerous proinflammatory cytokines, including tumour necrosis factor (TNF)-α, interferon (IFN)-γ, interleukin (IL)-17, IL-22, IL-23 and IL-1β." (PMID 36428539, 2022). "Thus, the results obtained in our study with quebecol and its derivatives indicate that the acanthosis and hyperplasia features of psoriasis could be mediated via the inhibition of IL-6 and TNF-α production." (PMID 35745702, 2022). "Collectively, STFs might be the targets of IL-17A and TNF-α antagonists for psoriasis and AD." (PMID 35669784, 2022). "Speculation includes a common genetic background linking psoriasis to Alzheimer's disease (AD), i.e., the APOE-ε4 allele, cardiovascular risk factors especially the metabolic syndrome, and tumor necrosis factor-α because of its role in neural functions as well as in inflammation." (PMID 35937394, 2022). "Also, psoriasis development was compared according to the types of anti-TNF agents." (PMID 35801760, 2022). "The obvious improvement of skin lesions in patients with psoriasis type 2 diabetes mellitus after liraglutide treatment may be related to inhibition of the expression of inflammatory factors such as IL-23, IL-17, and TNF-α." (PMID 36569936, 2022). "Thus, combined therapies of anti-TNF-α (or anti-IL-23/IL-17) and anti-IL-22 intervention might be effective in anti-TNF-α (or anti-IL-23/IL-17)-resistant psoriasis individuals." (PMID 35911703, 2022). "As one of the crucial inflammatory factors in psoriasis progression, TNF-α could promote KCs proliferation, aggravate inflammation and facilitate ROS production/accumulation through mediating inflammatory and OS-related signal pathways e.g. HO-1, JAK/STAT, PI3K/AKT, NF-κB, etc." (PMID 36178125, 2022). "Therefore, we have considered that steatohepatitis may exacerbate IMQ-induced psoriasis-like dermatitis by elevating TNF-α through systemic inflammation." (PMID 36555497, 2022).
psoriasis (continued). "Thus, data available to date (both molecular and functional) provide evidence on significantly impaired macrovascular endothelial function in psoriasis patients, possibly induced by the modulation of inflammatory responses (involving TNF-alpha, IL-17A) and increased levels of oxidative stress." (PMID 35883760, 2022). "Although the pathogenesis of psoriasis is not yet fully understood, recent studies have suggested that disturbances in innate and adaptive cutaneous immune responses, especially the interleukin (IL)-23/Th17 axis and TNF-α signaling, are critically involved in disease development." (PMID 35163233, 2022). "Nicotine is known to induce cytokine production, specifically increasing levels of tumor necrosis factor (TNF), interleukin-12 (IL-12), interleukin-2 (IL-2), and granulocyte-monocyte colony-stimulating factor, all of which are considered central to the pathophysiology of psoriasis." (PMID 35847770, 2022). "Notably, the pathogenesis of psoriasis is considerably mediated by T helper (Th) type 1 activation and Th17 immune responses and the consequent overproduction of cytokines (e.g., Tumor necrosis factor-α TNF-α, IL-23, and IL-17) that ultimately generate a systemic proinflammatory environment." (PMID 35686132, 2022). "Interestingly, the authors found that a single dose of NF-κB decoy ODN delivered via the combination of IP and the AT1002 analog peptide showed improved therapeutic effects against psoriasis, which significantly suppressed epidermal hyperplasia as well as the production of TNF-α and IL-6 mRNA." (PMID 35335900, 2022). "Furthermore, psoriasis patients may be treated with biological therapies targeting TNF-α, IL-17, and IL-23." (PMID 35888633, 2022). "Low levels of 5-HT increase the production of some inflammatory mediators, such as TNF-α and IL-1β, which induces the activation and deterioration of keratinocytes via NF-kB, which is activated by IL-17A in the prefrontal cortex and in the hippocampus, thus worsening the symptoms of psoriasis." (PMID 35335319, 2022). "Many immune-derived cytokines and chemokines, including IL-17, IL-23, IL-6, C-X-C motif ligand-1 (CXCL-1), TNF-α, and p65, can drive inflammatory cell infiltration and an inflammation loop, thus regulating keratinocyte proliferation and leading to the development and maintenance of psoriasis." (PMID 35216231, 2022). "Furthermore, the pathophysiology of psoriasis goes beyond this manuscripts TNF focus." (PMID 36605199, 2022). "In the present study, we have identified seven genetic loci that show evidence of influencing anti-TNF treatment response based on a meta-GWAS in 177 Chinese psoriasis patients, which might serve as predictors for treatment and guide personalized therapeutic decisions." (PMID 36059983, 2022). "In particular, TNF alpha inhibitors (etanercept and adalimumab), IL-17 inhibitors (ixekizumab, secukinumab), and IL-12/23 inhibitors (ustekinumab) are available for pediatric use and do not appear to have any interactions from the point of view of psoriasis metabolic complications." (PMID 35885717, 2022). "Recently, the IP-mediated delivery of the TNF-α drug etanercept, the ultrasound-mediated delivery of miR-197, and the fractional laser-mediated delivery of small interfering RNA (siRNA) targeting interleukin-6 have all demonstrated promising results against the pathogenesis of psoriasis." (PMID 35335900, 2022). "Indeed, stimulation of skin organ cultures with TNFα, IL-17, osteopontin, or IL-33, cytokines known to be central in the pathogenesis of psoriasis stimulated the expression of pro-osteoclastogenic factors in the skin that in turn promoted the differentiation of monocytes into osteoclast precursors." (PMID 35812457, 2022).
psoriasis (continued). "The treatment of psoriasis mainly includes topical therapies such as topical corticosteroids; vitamin D analogs; keratolytic agents; phototherapy; systemic therapies such as biologics targeting the proinflammatory cytokines TNF-α, IL-17, and IL-23; and oral systemic therapy." (PMID 36110097, 2022). "Thus, further long-term and large-scale studies are warranted to identify whether anti-IL-17 agents or TNF inhibitors have benefits on psoriasis with MetS." (PMID 34367173, 2021). "The reason may be thatYisaipu® is an TNF receptor fusion protein, while the therapeutic effect of monoclonal antibody anti-TNF agents on extraarticular manifestations such as psoriasis, uveitis and inflammatory bowel disease is better than that of TNF receptor fusion protein." (PMID 34552481, 2021). "Here, for the first time, we observed that IL-17B expression increased in the mesenchymal cells in the skin dermis region, possibly upon TNF-α stimulation during psoriasis, which could subsequently trigger DCs activation and potentially other immune cells via binding to its receptor IL17-RB." (PMID 33958582, 2021). "Psoriasis is a heterogenous disease, where >80 genes and alleles were described to increase disease susceptibility, including HLA-Cw6, PSOR1-15, CCHCR1, CDSN along with the range of inflammatory molecules regulated by the TNF-α signaling pathway in T helper (Th) cells." (PMID 34447766, 2021). "Thirty psoriasis patients were subjectedto a ketogenic nutritional regimen and monitored by evaluating (i)the clinical symptoms, (ii) the blood biochemical parameters, includingIL-2, IL-1β, TNF-α, IFN-γ, and IL-4, and (iii) themetabolomic profile, as derived from 1H NMR analysis." (PMID 33164516, 2021). "Moreover, there was a notable decrease in the levels of TNF-α, IL-22, and IL-17 compared to actual treatment, suggesting that the use of lipospheres could be interesting in the development of new treatments for psoriasis." (PMID 34067151, 2021). "The regulation of TNF half-life by Reg-3 might be of relevance to psoriasis." (PMID 34298932, 2021). "Therapeutic neutralization of TNF and IL-17 with mAbs resulted in a rapid recovery of pigmentation-related gene expression in psoriasis lesions, indicating IL-17 and TNF can affect pigment production in melanocytes, which may contribute to the hypopigmentation associated with psoriasis." (PMID 33921371, 2021). "Some patients, for example, might experience diminished response to anti-TNF drugs over time or develop a paradoxical exacerbation of PsO; similar cases of paradoxical psoriasis have been reported for secukinumab (anti–IL-17 monoclonal antibody) and ustekinumab (IL-12/23 inhibitor)." (PMID 34631754, 2021). "On the other hand, adalimumab is a widely used monoclonal antibody that targets against the proinflammatory cytokine TNF-α or affects the expression profiles of genes involved in the pathophysiology of diseases for the treatment of inflammatory and autoimmune diseases including RA and psoriasis." (PMID 34880764, 2021). "Moreover, an obviously improvement in M1-related inflammation medicators (TNF-α, IL-6, NO and iNOs) and suppression in M2-related anti-inflammation cytokines (IL-10 and Arg-1) emerged in psoriasis lesions in the skins of IMQ-treated mouse, which was consistent with previous reports." (PMID 33858431, 2021). "Indeed, psoriasis is reported to involve an upregulation of various immune cells (plasmacytoid dendritic and T helper cells), as well as the release of key cytokines such as TNF-a, interleukin-23 (IL-23), IL-17 and IL-22." (PMID 34680331, 2021). "In terms of treatment, anti-TNF immune-targeted therapy, such as adalimumab, and skin-directed therapy, such as ultraviolet B phototherapy, can reduce skin inflammation in patients with psoriasis, but adiponectin-induced glucose levels or insulin resistance do not change." (PMID 34372872, 2021).